INS (insulin)
Diseases named in the same sentence as INS in open-access papers (continued):
Sharing a sentence is not in itself a finding about the gene and the disease.
Hyperglycemia (continued). "We hypothesized that general anesthesia with a volatile agent would suppress basal insulin secretion without altering hepatic extraction and that subsequent surgical stress would promote hyperglycemia through protein catabolism, lipid oxidation, and uncoupled glucose‐insulin homeostasis." (PMID 36808704, 2023). "Although hyperglycemia may not be the only driver of diabetic neuropathy, it may predispose to IAPP-induced hypersensitivity because hIAPP-induced cell toxicity is exacerbated by hyperglycemia-induced glycated insulin." (PMID 36917177, 2023). "Survival and/or accelerated regrowth of IENF may reflect increased circulating insulin levels in the early stage, despite decreasing levels in the later stage, as sensory neuron energy balance, neurite outgrowth, and paw IENF density are modulated by insulin, independent of hyperglycemia." (PMID 35967127, 2022). "Management of post-prandial hyperglycemia of diabetic patients by acting on glucose transporters such as SGLT-1 or GLUT2 in this present paper could represent a real opportunity, first to decrease glucose absorption and second to restore the gut-brain axis to treat insulin resistance." (PMID 35631317, 2022). "Importantly, prediabetic hyperglycemia rapidly induced tissue‐specific programs, hallmarked by AKT phosphorylation, de novo lipogenesis, and an inhibition of gluconeogenesis in liver, as well as activation of insulin secretion, UPR, and ER stress in pancreatic islets." (PMID 36285680, 2022). "Therefore, cardiac specific silencing NEU1 does not affect insulin sensitivity or hyperglycemia." (PMID 35002528, 2022). "Conversely, early insulin therapy of preterm infants without severe hyperglycemia may be harmful." (PMID 35989990, 2022). "In contrast, hyperglycemia in non-diabetic patients may reflect increased sympathetic nervous system (SNS) activation and stressful state because the SNS is associated with the regulation of glucose level via the inhibition of insulin secretion." (PMID 36575485, 2022). "In COVID-19, ACE2 dysregulation by SARS-CoV-2 leads to marked elevation of vasoconstrictor AngII with a reduction in the vasodilator Ang1-7, which per se leads to pancreatic β-cell dysfunction, inhibition of insulin secretion, and hyperglycemia, which might be transient even in non-DM patients." (PMID 34124187, 2021). "Therefore, this peptide inhibits hyperglycemia without altering plasma insulin levels." (PMID 34445273, 2021). "Interestingly, insulin/IGF may also stimulate normal cells that could assist in cancer progression, as hyperglycaemia allows IGF-1 to stimulate vascular smooth muscle cell proliferation and migration leading to abnormal vasculature growth, a hallmark of cancer." (PMID 34535145, 2021). "Investigation of ADAM17 upregulation in COVID-19 patients, a comparison of the outcomes of diabetic patients with and without insulin (or different brands of insulin) treatments for the management of hyperglycemia, might answer the dilemma of appropriate sugar maintenance and possibly save lives." (PMID 34554559, 2021). "Finally, we should note that insulin treatment did not fully recover the morphological changes in bone likely because of insufficient blood glucose control as evidenced by episodes of hypo‐ and hyperglycemia." (PMID 33977201, 2021). "If hyperglycemia is not optimally controlled at the maximum tolerated dose of metformin, another oral agent such as dipeptidyl-4 inhibitors, glitazones, or a sulfonylurea may be considered before commencement of insulin." (PMID 34830886, 2021). "We aimed to estimate the prevalence and severity of hyperglycaemia during pulmonary exacerbations in paediatric CF patients not on insulin, to determine whether hyperglycaemia improved at the end of exacerbation treatment and whether it remained stable after return to baseline respiratory status." (PMID 33855211, 2021).
Hyperglycemia (continued). "The decreased insulin secretion is partly due to decreased beta-cell function mass seen in both lean and obese individuals and additional functional defects of pancreatic insulin secretion, leading to blindness and hyperglycemia, which is more marked in the non-obese group." (PMID 32399348, 2020). "However, an extensive work of pancreatic β-cells to secrete insulin into bloodstream is ultimately pointless, as the vicious cycle of IR is starting to develop, finally leading to a further decrease of available insulin-stimulated GLUT-4 in the cellular membrane and hyperglycemia." (PMID 32962281, 2020). "Notably, the normal inflammatory process seems to depend on the availability of insulin, and an impaired response to OVA in diabetic subjects may be primarily linked to an ongoing insulin deficiency rather than secondary hyperglycemia." (PMID 32117245, 2020). "Specifically, a meta-analysis that reviewed 11 randomized controlled trials involving 388 subjects reported that resveratrol could reduce hyperglycemia and improve insulin sensitivity in diabetic patients, but could not affect levels of glucose in nondiabetic patients." (PMID 31935938, 2020). "Thus, the hyperglycaemia that occurs in CB2−/− mice may be responsible for the higher level of glucokinase in the pancreatic islets, which might be a way to compensate for lower plasma insulin levels." (PMID 32365865, 2020). "In our model in which chronic hyperglycemia was sustained for 8 weeks, preoperative and postoperative phagocytosis activities of neutrophils were restored by insulin therapy for 5 days before the operation but not by insulin therapy for 6 h before the operation." (PMID 32993618, 2020). "Thus, leptin may sensitize neurons in the hypothalamus to the effects of insulin but may also exert central effects independent of insulin, as is supported by the fact that leptin can reverse hyperglycemia in mice with streptozotocin-induced type 1 diabetes." (PMID 31133864, 2019). "For instance, a meta-analysis for all available randomized controlled trials comparing the effect of green tea or green tea extract on insulin sensitivity and glycemic control could not confirm the efficacy of green tea in regulating postprandial hyperglycemia." (PMID 31277259, 2019). "These insulin delivery findings with closed-loop system use are not unusual in young patients with T1D who may not be receiving sufficient insulin to reach appropriate glycemic control; as indicated by higher baseline hyperglycemia, glucose variability, and HbA1c levels." (PMID 30585770, 2019). "While serum insulin was not increased in exercised IL-6−/− mice treated with olanzapine, the rise in blood glucose was prevented in these animals providing evidence that protection against olanzapine-induced hyperglycemia with exercise is not mediated by increases in circulating insulin." (PMID 29335597, 2018). "However, the lack of insulin resulting from the damage of the insulin-producing cells produces hyperglycemia that can also increase Aβ aggregation, making it difficult to elucidate if the increases in extracellular Aβ are due to the hypoinsulinemia and/or the glucotoxicity." (PMID 29743868, 2018). "Yet, the fact that an increase in MVPA was associated with improvements in 2hPG and insulin sensitivity, but not with reductions in FPG levels, support the notion that fasting hyperglycemia is not modifiable by lifestyle factors to the same extent as hyperglycemia after an OGTT." (PMID 28973497, 2017). "However, information about whether insulin therapy stimulates or suppresses the beta-cell response during permissive, stress-induced hyperglycemia in critically ill T2DM patients has not been studied." (PMID 28497374, 2017).
Hyperglycemia (continued). "However, there are currently no data on the use of CGM to inform insulin management of neonatal hyperglycaemia, although the use of CGM in conjunction with an insulin infusion was reported to reduce the number of episodes of hypoglycaemia in a baby with neonatal diabetes." (PMID 29051825, 2017). "However, it is not easy to determine the right dose of insulin; it may lead to hyperglycemia if not enough insulin has been administered." (PMID 28701182, 2017). "However, how hyperglycaemia and insulin dysfunction affect tau pathology, is not well understood." (PMID 28402338, 2017). "Curiously, there are some reports suggesting that resveratrol could also decrease hyperglycemia in streptozotocin (STZ)-induced diabetic rats, an insulinopenic model of DM considered a T1D-like condition, in which amelioration of pancreatic insulin secretion would be unexpected." (PMID 27366200, 2016). "This was formally established in our own Akita colonies not only by circulating insulin levels that did not rise with onset of hyperglycemia, but also by circulating C-peptide I and II (the same parameters followed in human patients) that may more closely reflect insulin secretion rates." (PMID 28702245, 2016). "Thus, the reduction in DN in intensive treatment group may be a result of restoration of the lost neuronal insulin signaling key to maintaining proper sensory function rather than just the control of hyperglycemia." (PMID 28066166, 2016). "However, evidence suggests that this is not the case as most cancers have highly effective upregulated, insulin-independent glucose uptake mechanisms and therefore may not derive a further growth advantage from hyperglycemia." (PMID 26983499, 2016). "However, it was reported in previous study that the acute sleep disturbance (24 h) could lead to hyperglycemia without changes in the insulin response." (PMID 27738407, 2016). "To clarify the molecular mechanisms underlying quetiapine-induced hyperglycaemia, we investigated toxicogenomics microarray datasets published in GEO (Accession No. GSE59923) by focusing on the expression of 24 gene products included in the KEGG “insulin resistance” pathway (Entry No. map04931)." (PMID 27199286, 2016). "Moreover, we found that 59% of the liver transplant recipients without pretransplant DM were discharged with insulin, and they would have required training in a whole new set of skills to monitor and manage their hyperglycemia before their transition to outpatient care." (PMID 28031946, 2016). "However, different from fasting hyperglycemia, postprandial hyperglycemia is not well controlled with basal insulin therapy and may be the limiting factor for achieving optimal glycemic control for many T2DM patients." (PMID 26594250, 2015). "The changes observed in the lambs from this study suggest that there could be long-term consequences to the increase in cortisol during late gestation on glucose disposal and on islet responses to basal, although not hyperglycemia-stimulated, insulin secretion." (PMID 26371232, 2015). "Unlike mammals, chickens naturally exhibit hyperglycemia (>200 mg/dL during fasting) and survive large doses of exogenous insulin, indicating an innate insensitivity to insulin, particularly in adipose tissue where insulin exerts only marginal effects on the uptake of glucose by isolated adipocytes." (PMID 26445145, 2015). "The effect of losartan was tested in isolation and not in combination with other antidiabetic therapies (e.g., insulin supplementation); therefore, some or many of the diabetic gene changes unaffected by losartan may represent the renal consequences of hyperglycemia, per se." (PMID 24827579, 2014). "In addition to ESC-derived insulin-producing cells, congenic mesenchymal stem cells have been shown to reverse hyperglycemia in diabetic nonobese diabetic (NOD) mice.Cord blood stem cells(CB-SCs) have displayed immunodulatory and anti-inflammatory capabilities in vitro." (PMID 25009980, 2014).
Hyperglycemia (continued). "As the decrease of the blood glucose level in alloxan induced mice where the pancreatic insulin synthesis was not possible, the estriol induced marked decrease of the blood glucose level in the alloxan treated mice implied an extra pancreatic synthesis of insulin for the control of hyperglycemia." (PMID 24711743, 2014). "Therefore, one could argue that hyperglycemia without insulin infusion does not confer a metabolic benefit and presents rather deleterious consequences on an ischemic heart." (PMID 25177798, 2014). "Another study suggests that hyperglycemia may not be concurrent with MS as it may occur later, when the function of the pancreas is challenged because of ongoing efforts to keep normal glucose levels through increased insulin production." (PMID 25713649, 2014). "Analyses of metabolic changes showed that high fat diet promoted hyperglycemia and hyperinsulinemia in male but not female 3xTg-AD mice, resulting in a significant interaction between sex and diet on fasting blood levels of glucose (F = 12.8, p<0.001) and insulin (F = 27.8, p<0.001)." (PMID 24205258, 2013). "However, unlike the sustained period of GPR40 knockout mice, in this experiment, although the serum insulin levels were reduced, treatment of DC260126 might start too late or last too short to fail to reverse the process of hyperlipidemia and hyperglycemia in db/db mice." (PMID 23776696, 2013). "The results suggest that although DC260126 could not provide benefit for improving hyperglycemia, it could protect against pancreatic β-cells dysfunction through reducing overload of β-cells, and it increases insulin sensitivity possibly via alleviation of hyperinsulinemia in db/db mice." (PMID 23776696, 2013). "The results presented here indicate that hyperglycemia alone is sufficient to induce the observed hepatic glycogenesis in 24H-fasted mice, and that an elevation of hepatic glycogenesis in the starved-state is not dependent upon a persistent rise in circulating insulin." (PMID 23861810, 2013). "This lower level of plasma IL-6 was correlated with the 64% lower post-meal hyperglycemia but not with the higher postprandial insulin levels suggesting that a decrease in post-meal hyperglycemia and not hyperinsulinemia directly, may be responsible for the lower plasma IL-6 levels." (PMID 23776669, 2013). "Therefore, our data suggest that addition of basal insulin to OAD is an effective approach for the management of hyperglycaemia in T2DM and intensification of insulin therapy with the addition of fast-acting pre-meal insulin may be necessary to achieve glucose targets." (PMID 23916120, 2013). "Because of their known impairment in insulin secretion, it seems contradictory for J mice to have lower plasma glucose levels than N mice, but the deletion in Nnt appears to affect glucose clearance rates only, and fasted or non-challenged J mice do not have constant hyperglycemia." (PMID 23902802, 2013). "These disparate responses suggest that hyperglycemia might compromise the function of the BBB during hyperbilirubinemia, while islets of Langerhans are more resistant to hyperbilirubinemia, and thus may preserve their insulin secreting capacity in response to hyperglycemia." (PMID 22811666, 2012). "Later on, with the decrease of serum insulin concentration and increase of α-cells, insulin could no longer efficiently suppress glucagon secretion, thus serum glucagon levels were high even in the presence of hyperglycemia." (PMID 22586489, 2012). "Moreover, the TD and PTD groups were better able to attenuate hyperglycemia compared with the D group, which may have mitigated the metabolic changes (despite the high glucose levels and absence of insulin) in these animals." (PMID 23144989, 2012).
Hyperglycemia (continued). "While it has been shown that intensive insulin therapy reduces the incidence of critical illness neuromyopathy and that hyperglycaemia worsens brain injury in ischemic stroke and head trauma, the effect of hyperglycaemia or insulin on sepsis related brain dysfunction is not well understood." (PMID 21612615, 2011). "Elevated insulin alone without hyperglycemia may have a damaging effect." (PMID 19695080, 2009). "Thus, hyperglycaemia develops but no glucose can enter into the cell of the insulin target tissues." (PMID 18353182, 2008). "Insulin administration prevented the decrease in EDL muscle mass, whereas phlorizin did not, despite improving hyperglycemia." (PMID 42164254, 2026). "Given that insulin is the only approved pharmacological treatment for GDM in many countries, there is a growing need for non-pharmacological interventions to manage hyperglycaemia safely and effectively." (PMID 41203981, 2026). "GLP-2 did not affect circulating concentrations of insulin, C-peptide, growth hormone, norepinephrine, or CTX during hypoglycemia, euglycemia, or hyperglycemia." (PMID 41541287, 2026). "p110α and p110β regulate insulin-driven PI3K/AKT signaling pathway; inhibiting it can lead to hyperglycemia, rather than p110 δ and p110 γ." (PMID 40041495, 2025). "Systemically, the intervention effectively alleviated hyperglycemia, HOMA-IR, hyperlipidemia, and serum MDA levels, reduced NAS and liver TNF-α levels, while having no appreciable effect on adiposity, serum insulin levels, or liver IL-6, TG, and TC levels." (PMID 40427484, 2025). "To further examine the effect of chronically elevated levels of insulin on the development of liver fibrosis in vivo, we used the L-SACC1 transgenic mouse model of hyperinsulinemia without fasting hyperglycemia." (PMID 40808720, 2024). "The acute, transient rise of insulin in the vagotomized animals at 3 h post-LPS was not fully recovered by efferent VNS, indicating the synergistic role of inflammation and hyperglycemia in this response." (PMID 38248469, 2024). "Though there are efforts to increase availability of oral hypoglycemics and insulin to the non-affording patients visiting IHHN, interventions should also be directed towards preventing hyperglycemia among pre-diabetic patients." (PMID 38328649, 2024). "During hyperglycemia, GIP potentiates glucose-induced insulin secretion without exhibiting a glucagonotropic effect." (PMID 39114288, 2024). "This study demonstrates that TDAG51-GFP restoration improved insulin sensitivity, while no changes were observed after a glucose challenge in TDAG51−/− mice, confirming the originally reported basal dysglycemia and hyperglycemia observed in these mice." (PMID 38237682, 2024). "Hyperglucagonemia, a hallmark of type 2 diabetes (T2DM) present in Zucker diabetic fatty (ZDF) rats, is not the primary mediator of hyperglycemia and high EGP as commonly thought; instead, the liver is resistant to glucagon as well as insulin and glucose." (PMID 38265288, 2024). "HFD leads to IR, dyslipidemia, and hyperglycemia, while STZ impairs insulin secretion, resulting in low insulin levels and progressive T2DM without external insulin administration." (PMID 39334757, 2024). "The genetic ablation of Ca2+-permeable non-selective cation channel TRPM2 results in defective insulin secretion in CD1 mice; consequently, TRPM2 KO mice fed a high-glucose diet develop hyperglycemia due to insufficient insulin release." (PMID 36674711, 2023). "In response to hyperglycemia, Kir6.2+/+ APP/PS1 mice also showed a 210% increase in plasma insulin compared with fasting levels (P = 0.002), while no change on plasma insulin levels was observed in Kir6.2–/– APP/PS1 mice (P = 0.8976)." (PMID 37129980, 2023).